LENG1 (leukocyte receptor cluster member 1)
Tractability: Antibody: the Human Protein Atlas places it where antibodies can reach. PROTAC: ubiquitination databases record sites on it; its protein half-life has been measured.
Gene: Protein-coding gene on chromosome 19 (54,155,161 to 54,159,721, reverse strand). Ensembl gene ENSG00000105617.
Subcellular location (Human Protein Atlas): Plasma membrane; Nucleoplasm
Pathways (Reactome):
Metabolism of RNA: mRNA Splicing - Major Pathway
Gene Ontology:
Molecular function: protein binding
Cellular component: nucleoplasm
Genetic constraint (gnomAD): Loss-of-function variants: 33 observed, 27.65 expected, observed/expected ratio (o/e) 1.19, 90% interval 0.9 to 1.59. The upper end of that interval is the gene's LOEUF score, 1.59, which puts it in group 6 of 6, group 1 being the genes least tolerant of losing a copy. Missense variants: 395 observed, 348.09 expected, observed/expected ratio (o/e) 1.13, 90% interval 1.04 to 1.23. Synonymous variants: 168 observed, 139.51 expected, observed/expected ratio (o/e) 1.2, 90% interval 1.06 to 1.37.
Homologues: Orthologues: chimpanzee LENG1 (97% identical), macaque LENG1 (94% identical), pig LENG1 (84% identical), rat Leng1 (83% identical), dog LENG1 (81% identical), mouse Leng1 (81% identical), guinea pig LENG1 (80% identical), rabbit LENG1 (80% identical), tropical clawed frog leng1 (57% identical), zebrafish leng1 (42% identical), Drosophila melanogaster CG12818 (36% identical), Caenorhabditis elegans Y18H1A.2 (31% identical).
Diseases named in the same sentence as LENG1 in open-access papers:
LENG1 is named in the same sentence as 1 disease in open-access papers, as found by Europe PMC text mining. Sharing a sentence is not in itself a finding about the gene and the disease. The quoted sentences say what the papers report.
infection (1 paper, 2017). The state of being infected such as from the introduction of a foreign agent such as serum, vaccine, antigenic substance or organism. "Out of these LENG1 and PPIL1 were also down regulated in H37Rv infected macrophages at 48 hours post-infection." (PMID 28257432, 2017).